C7orf57 (chromosome 7 open reading frame 57)
Synonyms: FCAP33
Tractability: No criterion of Open Targets' tractability assessment is met for any kind of drug.
Gene: Protein-coding gene on chromosome 7 (48,035,501 to 48,061,304, forward strand). Ensembl gene ENSG00000164746.
Subcellular location (Human Protein Atlas): Cytosol; Basal body; Primary cilium; Primary cilium transition zone
Genetic constraint (gnomAD): Loss-of-function variants: 27 observed, 31.38 expected, observed/expected ratio (o/e) 0.86, 90% interval 0.63 to 1.19. The upper end of that interval is the gene's LOEUF score, 1.19, which puts it in group 5 of 6, group 1 being the genes least tolerant of losing a copy. Missense variants: 320 observed, 331.05 expected, observed/expected ratio (o/e) 0.97, 90% interval 0.88 to 1.06. Synonymous variants: 119 observed, 126.7 expected, observed/expected ratio (o/e) 0.94, 90% interval 0.81 to 1.09.
Homologues: Orthologues: chimpanzee C7H7orf57 (99% identical), chimpanzee C7H7orf57 (93% identical), macaque C3H7orf57 (88% identical), pig C7orf57 (75% identical), mouse Gm11992 (74% identical), guinea pig C7orf57 (73% identical), rabbit C7orf57 (73% identical), rat C14h7orf57 (72% identical), dog C7orf57 (69% identical), tropical clawed frog c6h7orf57 (38% identical), zebrafish si:dkey-276j7.1 (20% identical).
Diseases named in the same sentence as C7orf57 in open-access papers:
C7orf57 is named in the same sentence as 4 diseases in open-access papers, as found by Europe PMC text mining. Sharing a sentence is not in itself a finding about the gene and the disease. The quoted sentences say what the papers report.
asthma (1 paper, 2020). "Among ten hub DEGs identified for the asthma-COPD, nine DEGs including SPAG6, C7orf57, SYTL3, LRRC48, TEKT3, CCDC146, CETN2, CCDC19, and C14orf45 were identified as the novel genes." (PMID 31952466, 2020).
glioma (1 paper, 2021). A benign or malignant brain and spinal cord tumor that arises from glial cells (astrocytes, oligodendrocytes, ependymal cells). "High DEGs in grade II gliomas included NNMT, MFAP5, APCDD1L-AS1, C7orf57, HP, SERPINA5, and LTF and some highly downregulated DEGs included ABCA4, PDE6A, GRP, RD3, and TMEM72." (PMID 33948562, 2021).
head and neck cancer (1 paper, 2021). A primary or metastatic malignant neoplasm affecting the head and neck. "In addition, we found under-expression of C7orf57, a gene that is expressed in ciliated nasal epithelial cells and has been downregulated with head and neck cancer and specifically NPC." (PMID 34648530, 2021).
C7orf57 also shares sentences with these, for which no sentence is quoted: sporadic amyotrophic lateral sclerosis (1 paper).